AR (androgen receptor)
Diseases named in the same sentence as AR in open-access papers (continued):
Sharing a sentence is not in itself a finding about the gene and the disease.
prostate carcinoma (continued). "PTEN deficiency facilitated p300 to bind and acetylate androgen receptor (AR) by increasing the phosphorylation of AR in prostate cancer cells." (PMID 32398948, 2020). "In fact, it was shown that AR loss in prostate cancer cells favors stem-like phenotype and triggers IL-6 production, which in turn activates Stat3." (PMID 31366128, 2019). "In the other way, prostate cancer small cell/neuroendocrine phenotype, an increasingly prevalent histologic subtype in castration resistant prostate cancer with low androgen receptor activity is also characterized by loss of RB expression." (PMID 30885218, 2019). "AR showed a broad spectrum of activity between genomic subtypes: ETS fusion-positive prostate cancers display a variable AR transcriptional activity; tumors with SPOP or FOXA1 mutations had the highest AR transcriptional activity." (PMID 31366128, 2019). "Differential methylation patterns of AR are also associated with prostate cancer, non-Hodgkin's lymphoma, and ovarian cancer." (PMID 30913233, 2019). "Many AR splice variants have been identified in prostate cancer and have been associated with the development of resistance to ADT, the most widely studied and clinically meaningful being the AR-V7 (or AR3) and the ARv567es (or AR-V12)." (PMID 30642011, 2019). "Castration‐resistant progression of prostate cancer is a major cause of prostate cancer mortality, and increased expression and activity of the full‐length and the splice variants of androgen receptor (AR) have been indicated to drive castration resistance." (PMID 30905075, 2019). "In particular, similar to the observations in prostate cancer, preclinical studies have demonstrated that activation of AR-related signals is generally associated with induction of urothelial tumorigenesis and tumor progression." (PMID 30791431, 2019). "To date, more than 20 AR splice variants (AR-V) have been identified in prostate cancer cell lines and mouse xenografts, some of which have been validated in human cancer." (PMID 31142021, 2019). "The most well studied signalling molecule activated by AR is the membrane-associated non receptor tyrosine kinase Src, which plays an important role in lethal prostate cancer." (PMID 30832393, 2019). "Molecular modifications of the androgen receptor (AR) can cause resistance to androgen deprivation therapy (ADT) in prostate cancer patients." (PMID 31289619, 2019). "More importantly, CWP232291 also downregulates AR and its splice variants in prostate cancer cells (22Rv1 and LNCaP)." (PMID 31387608, 2019). "Various mechanisms are responsible for the adaptation of prostate cancxer tumors to ADT and include point mutations in androgen receptor, AR amplification, changes of androgen biosynthesis, changes in AR cofactor in prostate cancer cells, AR variants." (PMID 31366128, 2019). "The ability to suppress EMT has also been noted in prostate cancer, another cancer driven by a steroid hormone receptor (AR), and the genes regulated by GRHL2 are linked to disease progression." (PMID 31084623, 2019). "hnRNPL was also involved in prostate cancer progression through regulating the alternative splicing of a set of RNAs, including those encoding androgen receptor, the key lineage-specific oncogene of prostate cancer." (PMID 31856843, 2019). "AR mutations or loss, which lead to androgen resistance in differentiated prostate cancers, contribute to TGF-β overexpression, stimulation of growth, viability, and aggressiveness of prostate cancer cells." (PMID 31842336, 2019). "Since the androgen/androgen receptor (AR) axis is associated with the pathogenesis of prostate cancer, suppression of AR-dependent signaling by androgen deprivation therapy (ADT) still represents the primary intervention for this disease." (PMID 31548498, 2019). "Advanced prostate cancer is often associated with reduced androgen receptor (AR) expression leading to castration-resistant cancer." (PMID 31360119, 2019).
prostate carcinoma (continued). "One of the mechanisms by which advanced prostate cancer develops resistance to androgen deprivation therapy is the elevated expression of C-terminally truncated androgen receptor (AR) variants." (PMID 30664691, 2019). "AR signaling has also been implicated in the pathogenesis and growth of malignancies, including not only prostate cancer for which androgen deprivation therapy remains the mainstay of management but also other types such as breast cancer and bladder cancer." (PMID 30791431, 2019). "Widespread studies of AR regulators in advanced prostate cancer have provided a better understanding of mechanisms underlying castration resistance." (PMID 30774773, 2019). "Inhibition of the AR signaling axis and AR target gene expression, as well as the subsequent loss of viability in AR-positive prostate cancer cell lines suggested that treatment with IRC117539 targets AR." (PMID 31431473, 2019). "Elucidation of mechanisms underlying the increased androgen receptor (AR) activity and subsequent development of aggressive prostate cancer (PrCa) is pivotal in developing new therapies." (PMID 30237440, 2019). "FOXA1 is a critical interacting partner of the nuclear hormone receptors, estrogen receptor (ERα) and androgen receptor (AR), which are associated with hormone-regulated cancers such as breast and prostate cancer." (PMID 30819139, 2019). "In many research articles, AR has been indicated as a possible cause for the progression and the development of prostate cancer." (PMID 30838019, 2019). "Loss of androgen receptor (AR) dependency in prostate cancer (PCa) cells is associated with progression to castration-resistant prostate cancer (CRPC)." (PMID 31484364, 2019). "The emergence of AR splice variants is proposed as a mechanism of treatment resistance: thus, AR-Vs have been implicated in the treatment failure of prostate cancer patients undergoing androgen deprivation therapy alone or in combination with radiotherapy." (PMID 31366128, 2019). "The androgen receptor (AR), a nuclear hormone transcription factor, directs the transcription of several genes implicated in the development and progression of prostate cancer (PCa)." (PMID 30367117, 2019). "Mutations and amplifications of AR lead to abnormal activation of androgen signaling to facilitate prostate cancer aggressive progression." (PMID 31581661, 2019). "The corepressors N-CoR and SMRT bind the androgen receptor (AR) and the estradiol receptor (ER), and their downregulation has been associated with breast and prostate cancer initiation, progression, and drug resistance." (PMID 31805753, 2019). "This study identifies RA as a new agent to target both the full‐length and the splice variants of AR and provides a rationale for further developing RA for prostate cancer treatment." (PMID 30905075, 2019). "This rebound is blocked by the combined addition of both a PI3Kalpha and a PI3Kbeta inhibitor; however, in PTEN-deficient mouse models of prostate cancer this efficient PI3K inhibition causes a marked activation of AR activity." (PMID 31366128, 2019). "In summary, we have identified TLE3 loss as a novel resistance mechanism to AR-targeted therapeutics in prostate cancer cells." (PMID 31855178, 2019). "While benign prostate cells are insensitive to SR-B1 antagonism, prostate cancer cells, particularly those expressing splice-variant AR, are inhibited by lowering SR-B1 expression/activity." (PMID 31366128, 2019). "Aggressive prostate cancer has been linked to Androgen Receptor (AR) activation, which occurs through multiple mechanisms, including intra-tumor androgen production." (PMID 31530281, 2019). "Through a genome-wide CRISPR-Cas9 screen we identified transducin-like enhancer of split 3 (TLE3) as a modulator of AR inhibitor sensitivity that, upon loss, confers resistance to enzalutamide in prostate cancer cells." (PMID 31855178, 2019).
prostate carcinoma (continued). "In prostate cancer, mRNA extracted from CTCs has been used to identify splice variants of the androgen receptor that are prognostic for taxane therapy." (PMID 31137920, 2019). "ARV7 expression in CTCs of prostate cancer patients has been linked to resistance toward AR-targeted therapy, in particular enzalutamide and abiraterone." (PMID 31514447, 2019). "Detection of androgen receptor (AR) variant 7 (AR-V7) is emerging as a clinically important biomarker in castrate resistant prostate cancer (CRPC)." (PMID 31288377, 2019). "AR signaling was shown as the crucial oncogenic driver of prostate cancer, it is also significantly associated with tumor progression in other solid tumors, such as lung, kidney, breast and bladder cancers." (PMID 31119584, 2019). "For example, there has been a report of the possible role played by adaptive mutation in the development of resistance to the androgen receptor antagonist bicalutamide in prostate cancer cells." (PMID 31861770, 2019). "One approach to identifying AR association with telomeres is dual-label immunofluorescence of AR that colocalizes with TIN2 in prostate cancer cells." (PMID 31083651, 2019). "Mechanisms of resistance in prostate cancer include androgen receptor (AR) mutations, AR amplification, AR splice variants, AR bypass pathways, drug efflux alterations and inhibition of cell death." (PMID 31234468, 2019). "Here, we describe a molecule, which selectively induces AR destruction, resulting in the loss of prostate cancer cell viability ex vivo." (PMID 31431473, 2019). "The point mutation of AR in the ligand-binding domain is reported in prostate cancer and more frequently in patients with castration-resistant disease." (PMID 31877956, 2019). "Together, our data shows that loss of TLE3 in conjunction with AR inhibition results in GR upregulation, leading to enzalutamide-resistance in LNCaP prostate cancer cells." (PMID 31855178, 2019). "Similar to the ERα results, studies with dihydrotestosterone- (DHT-) treated prostate cancer cells also showed AR association with an enhancer involved in AR activation of specific genes." (PMID 31275057, 2019). "In short, the pathological roles of AR in CAFs are well-implicated in the development of prostate cancer, making it an attractive therapeutic target." (PMID 30925918, 2019). "Majority of the AR point mutations in prostate cancer have been identified in the LBD suggesting their importance in pathobiology associated with aberrant AR signaling." (PMID 31877956, 2019). "A small molecule inhibitor against HSP90 phosphorylation at the level of Thr-89 residue, in association with an AR antagonist, was more potent than androgen deprivation alone in inhibiting the proliferation of prostate cancer cells." (PMID 31366128, 2019). "In patients with double primary cancers of the prostate and the bladder, androgen-deprivation therapy (ADT) to treat their prostate cancers reduced the risk of recurrence of AR+ BC." (PMID 30961575, 2019). "Critically, ex vivo, IRC117539-mediated AR degradation induces prostate cancer cell viability loss by inhibiting AR signaling, even in androgen-insensitive cells." (PMID 31431473, 2019). "Taken together, these findings suggest that deregulation of the MYC/E2F1/RB1 cell-cycle regulator axis by various means is a ubiquitous event in AR indifferent prostate cancer that is necessary to overcome the G1 arrest caused by low AR activity." (PMID 31551480, 2019). "DNAH8 has been reported to be a novel regulator of the androgen receptor that is associated with metastatic tumors and poor prognosis in patients with prostate cancer." (PMID 30944005, 2019). "The SALV-ENZA trial is the first phase II placebo-controlled double-blinded randomized study to test SRT in combination with a next generation androgen receptor antagonist in men with high-risk recurrent prostate cancer after radical prostatectomy." (PMID 31196032, 2019).
prostate carcinoma (continued). "Another study shows that nucleosomes containing acetylated H2A.Z are incorporated at enhancers associated with AR activity and contribute to the formation of neo-enhancers in prostate cancer." (PMID 31200487, 2019). "We have shown a significant association between low AR levels in cancer-associated stroma and increased prostate cancer-related death at 1, 3, and 5 years post-diagnosis." (PMID 29721186, 2018). "The sclerotic phenotype of bone metastases seen in prostate cancer patients suggests a possible association between locally excessive bone formation and AR activity." (PMID 29670000, 2018). "The first AR co-activator identified was Androgen Receptor Associated protein 70 (ARA70) in prostate cancer." (PMID 30416486, 2018). "More broadly, a recent study highlights the important role of histone acetylation in prostate cancer beyond active promoters via activation of AR associated enhancers and the increase in chromatin accessibility [95•]." (PMID 29888169, 2018). "To date, studies on primary prostate cancer have provided insight into the drivers of the disease, mostly focusing on Androgen Receptor (AR) function, mRNA expression, DNA copy number and mutations, as well as deviations in protein expression." (PMID 30464211, 2018). "CaMKK2 is a known tumor promotor whose expression is linked to the upregulation of the androgen receptor, a key step in castrate-resistant prostate cancer." (PMID 29914450, 2018). "Emerging studies have shown that the expression of AR splice variants (ARv), which lack a ligand-binding domain, is increased in androgen-independent prostate cancer cell lines, CRPC, and metastatic PCa." (PMID 30450161, 2018). "PCAT3, also known as PCA3, is one of the most specific prostate cancer diagnostic biomarker involved in controlling prostate cancer cell surviving and modulating androgen receptor signaling." (PMID 29552304, 2018). "In metastatic castrate resistant prostate cancer there is frequently over-expression of both full length AR (AR-FL) and AR variants (AR-V)." (PMID 30180883, 2018). "We have reported that loss of AR expression in prostate cancer-associated fibroblasts is a poor prognostic indicator." (PMID 29721186, 2018). "Collectively, these findings suggest that loss of ELF3 represents an additional means of enhancing AR activity in prostate cancer cells." (PMID 30200227, 2018). "Prostate cancer (PCa), a leading cause of cancer-related death in men, becomes resistant to androgen deprivation therapy by inducing androgen receptor (AR) activity, which is known as castration-resistant PCa (CRPC)." (PMID 30177856, 2018). "Secondly, HDACIs have been associated with the interruption of the AR pathway, which makes HDACIs somehow efficient for the treatment of prostate cancer." (PMID 29523594, 2018). "Depletion of HDAC3 or other HDACs suppresses expression of AR and its downstream target genes in prostate cancer cells, although the underlying mechanism remains poorly understood." (PMID 29523594, 2018). "On the other hand, approximately 25% of the men who die of prostate cancer have tumors with a neuroendocrine phenotype associated with low AR signaling and poor prognosis." (PMID 30287808, 2018). "Androgen-receptor splice variant 7 (AR-V7) is a constitutively-active isoform of the androgen receptor that is associated with a particularly aggressive form of advanced prostate cancer." (PMID 29983880, 2018). "Prostate cancer has recently entered the arena of the biomarker-addicted tumour, following the discovery that a splice variant of the androgen receptor (AR-V7), tested on CTCs, drove resistance to hormonal treatment." (PMID 30430428, 2018). "The levels of expression of AR-Vs are increased in castrate resistant prostate cancer, in response to AR blockade and associated with disease progression." (PMID 30180883, 2018).
prostate carcinoma (continued). "Most importantly, the Cancer Genome Atlas (TCGA) data demonstrate that SPOP‐mutated prostate cancers exhibit the highest AR activity among all molecular subtypes of prostate cancer examined." (PMID 29523594, 2018). "Liang and coworkers used variants of LNCaP prostate cancer cell lines todemonstrate that antiandrogen-resistant LNCaP cell lines with an AR-rich phenotype have a G1cell cycle blockade in the presence of androgens by regulating cMyc, Skp2 andp27kip via the AR." (PMID 29162647, 2018). "Our group previously reported the identification of two H2A.Z isoforms: H2A.Z.1 and H2A.Z.2 and described the association of H2A.Z.1 with androgen receptor dependent prostate cancer progression." (PMID 30651935, 2018). "The eight proteins highlighted in this study (KLK3, SORD, SPON2, IMPDH2, ACTN4, ATP1B1, HSPB1, and KHDRBS1) represent a signature associated with AR modulation during the transition from androgen-dependent to castration-resistant prostate cancers." (PMID 29966326, 2018). "Below, we show that the progenitor properties of CARNs are largely unaffected by loss of AR, whereas their ability to serve as cells of origin for prostate cancer are altered by AR deletion in a context-dependent manner." (PMID 29334357, 2018). "Accordingly, GATA2 activity in human prostate cancer is strongly associated to AR levels and is hence considered a prostate cancer oncogene." (PMID 29888169, 2018). "To further explore the association of TLX and AR expression in primary prostate cancer and CRPC, we compared TLX levels in ARlow and ARhigh subsets of prostate cancer patients using RNA-seq datasets in two published cohorts in an unbiased manner." (PMID 29555975, 2018). "The AR also associates with PRMT9/10 in the prostate cancer cell line, LNCaP, and knockdown of PRMT9/10 suppressed both cellular growth and expression of the prostate specific antigen (PSA)." (PMID 29568320, 2018). "AR expression has also been detected in prostate cancer-associated fibroblasts (CAFs) in vitro and siRNA-mediated depletion of AR from these stromal cells resulted in a decrease in FGF10 expression." (PMID 30405704, 2018). "AKT‐mTOR and androgen receptor (AR) signaling pathways are aberrantly activated in prostate cancer due to frequent PTEN deletions or SPOP mutations." (PMID 29523594, 2018). "This approach focused on constitutively active androgen receptor (AR) splice variant‐driven pathways as representative of an intractable mechanism of prostate cancer (PC) therapeutic resistance." (PMID 30108134, 2018). "Constitutively active androgen receptor (AR) variants confer anti-androgen resistance in advanced prostate cancer." (PMID 30446660, 2018). "They show in cells that ARCC-4 is more effective than the prostate cancer drug enzalutamide and can degrade androgen receptor variants resistant to enzalutamide." (PMID 30271980, 2018). "Previously, we showed in a cohort of 64 patients that low AR expression is significantly associated with prostate cancer-related death at 1, 3, and 5 years post-diagnosis." (PMID 29721186, 2018). "Our results will enable design of improved prostate cancer treatments and facilitate endocrine disruption chemical risk assessment through AR-mediated responses." (PMID 29867496, 2018). "We next investigated the effects of SPRY2 on growth under hormone deprivation in LNCaP cells, an AR‐proficient prostate cancer cell line deficient for both SPRY2 and PTEN (Fig EV1K)." (PMID 29540470, 2018). "SRC-3 (AIB1) is a known AR co-activator in prostate cancer, and is associated with a poor prognosis in breast cancer." (PMID 30416486, 2018).